CCNG2 (cyclin G2)
Diseases named in the same sentence as CCNG2 in open-access papers (continued):
Sharing a sentence is not in itself a finding about the gene and the disease.
triple-negative breast carcinoma (3 papers, 2015 to 2023). An invasive breast carcinoma which is negative for expression of estrogen receptor (ER), progesterone receptor (PR), and human epidermal growth factor receptor 2 (HER2). "Forced expression of miR-130b-5p was found to significantly repress the endogenous expression levels of CCNG2 in triple-negative breast cancer cells." (PMID 25888956, 2015). "Of added interest, recently CCNG2 was found to be an important prognostic factor for triple-negative breast cancer patients." (PMID 25888956, 2015). "A direct correlation between high miR-130b-5p expression (p <0.001; fold change 2.8) and low CCNG2 expression (p <0.001; fold change 0.5) was observed in our triple-negative breast cancer samples as compared with normal breast tissue controls." (PMID 25888956, 2015). "The gene expression levels of CCNG2 in triple-negative breast cancers (n = 51) were significantly lower (p <0.001; fold change 1.9) than those in normal breast tissues (n = 25) in the microarray data." (PMID 25888956, 2015). "Gene expression levels of CCNG2 between triple-negative breast cancers and normal breast tissues were further investigated using a published microarray dataset [GEO:GSE53752]." (PMID 25888956, 2015). "We were able to identify CCNG2 as a direct target of miR-130b-5p in triple-negative breast cancer." (PMID 25888956, 2015). "The findings described in this study implicate a miR-130b-5p-CCNG2 axis that may be involved in the malignant progression of triple-negative breast cancer." (PMID 25888956, 2015). "It would be interesting to test whether this novel regulatory mechanism of miR-130b-5p and its CCNG2 target in triple-negative breast cancer may be involved in other malignancies as well." (PMID 25888956, 2015). "Moreover, we extended the current knowledge of microRNA regulatory network by showing that miR-130b-5p in the miR-301b-130b cluster directly silences CCNG2 in triple-negative breast cancer." (PMID 25888956, 2015). "Next, we examined whether miR-130b-5p might repress endogenous CCNG2 expression in triple-negative breast cancer cells." (PMID 25888956, 2015). "In triple-negative breast cancer cells, lncRNA GAS5 promotes cancer cell apoptosis by targeting miR-378a-5p, and the targeting relationship of miR-378a-5p and cyclin G2 has been confirmed by luciferase reporter assay in BeWo cells." (PMID 37025425, 2023). "Moreover, miR-130b-5p from the miR-301b-130b cluster was shown to directly repress the cyclin G2 (CCNG2) gene, a crucial cell cycle regulator, in triple-negative breast cancer cells." (PMID 25888956, 2015).
astrocytoma (2 papers, 2018 to 2025). "Our results support accumulating evidence that the expression of CCNG2 diminishes as cancer progresses, with the lowest expression of CCNG2 associated with a more advanced stage of astrocytoma." (PMID 29720957, 2018). "Paratumor compared samples sections were stained more intensely with 3,3′-diaminobenzidine indicating a higher presence of CCNG2 than in low and high grades of astrocytoma." (PMID 29720957, 2018). "In this study, we investigate CCNG2 expression and its inhibitory function in surgical samples and human astrocytoma cells." (PMID 29720957, 2018). "The present study highlights the regulatory consequences of CCNG2 expression and AKT activity in astrocytoma tumorigenesis and the potential use of CCNG2 in anticancer treatment." (PMID 29720957, 2018). "The CCNG2 level in the low-grade astrocytoma (n = 31) was also higher than that of the high-grade astrocytomas (P < 0.01)." (PMID 29720957, 2018). "Low expression of CCNG2 was correlated with the severity of astrocytoma." (PMID 40570725, 2025). "Finally, the relationships between CCNG2 expression and clinicopathological characteristics of astrocytomas were analyzed." (PMID 29720957, 2018). "In this study, we examined the relationship between CCNG2 and the malignancy of astrocytomas and whether the AKT pathway, which is upregulated in astrocytomas, may inhibit CCNG2 expression." (PMID 29720957, 2018). "CCNG2 expression correlated with the pathological grade of astrocytoma, with the highest level of expression found in paratumor compared samples (n = 31) and the lowest expression found in high-grade astrocytomas (n = 31, P < 0.001)." (PMID 29720957, 2018). "To determine whether the expression of CCNG2 was influenced by the grade of astrocytoma, we assessed CCNG2 mRNA expression and protein levels in paratumor compared samples to low- and high-grade astrocytoma tissue." (PMID 29720957, 2018). "To conclude, low expression of CCNG2 correlated with the severity astrocytoma and CCNG2 overexpression could induce apoptosis and inhibit proliferation." (PMID 29720957, 2018). "Based on our data, we believe that the regulation of CCNG2, possibly by the AKT pathway, has potential in the management of astrocytomas." (PMID 29720957, 2018).
bladder tumour (2 papers, 2005 to 2025). "Cyclin G2 RNA levels were shown in another array to be expressed at a lower level in stage T2 bladder tumours than in Ta." (PMID 16052224, 2005). "We found that seven of these genes, IGFBP3, VEGF, CCNG2, NDRG1, PFKFB3, ADM and SLC2A1, were also upregulated in MIBC and/or NMIBC in our study, suggesting parallel hypoxia-induced expression changes with primary bladder tumour tissue." (PMID 40867253, 2025).
COVID-19 (2 papers, 2024 to 2025). A disease caused by infection with severe acute respiratory syndrome coronavirus 2. "Within the dataset analyzed in this study, 4 out of 27 genes (14,8%) showed the 3′UTR shortening mechanism via APA (Δusage < −0.3), providing specific examples of potential escape from miRNA regulation in COVID-19 patients: CCNG2, PGS1, RTF1 and SPCS3." (PMID 41168347, 2025).
diabetes (2 papers, 2018 to 2020). "To evaluate the effects of cyclin G2 inhibition on canonical Wnt signalling in diabetes, we assessed protein expression levels of Wnt signalling factors in the renal tissues of Ccng2−/− and WT DN mice." (PMID 30420966, 2018). "To evaluate whether cyclin G2 protects against renal dysfunction developed in diabetes, we assessed blood glucose, 24‐hour urinary albumin, urinary creatinine, body weight and kidney weight in our animal model." (PMID 31978940, 2020). "Taken together, these data suggest that cyclin G2 may be involved in the pathological processes of diabetes." (PMID 30420966, 2018). "Hence, cyclin G2 might attenuate tubulointerstitial fibrosis and relieve renal injury in this animal model of diabetes by decreasing the changes in fibrosis‐related proteins induced during the development of DN." (PMID 31978940, 2020). "Therefore, cyclin G2 appeared to ameliorate renal injury in a diabetes mouse model." (PMID 30420966, 2018). "Cyclin G2 expression was evaluated by Western blotting using the renal tissue homogenate of normal mice and those with STZ‐induced DN at 16 weeks after the onset of diabetes." (PMID 31978940, 2020).
diabetic nephropathy (2 papers, 2018 to 2020). "Cyclin G2 in the occurrence and development of diabetic nephropathy (DN), one of the most severe diabetic complications, has not been fully identified." (PMID 31978940, 2020). "The involvement of cyclin G2 in the occurrence and development of diabetic nephropathy (DN) has not been determined." (PMID 30420966, 2018).
head and neck squamous cell carcinoma (2 papers, 2021 to 2023). A squamous cell carcinoma that arises from any of the following anatomic sites: lip and oral cavity, nasal cavity, paranasal sinuses, pharynx, larynx, and salivary glands. "CCNG2 inhibits cell cycle progression in head and neck squamous cell carcinomas and Raji lymphoma cells." (PMID 37204480, 2023).
leukemia (2 papers, 2015 to 2018). A malignant (clonal) hematologic disorder, involving hematopoietic stem cells and characterized by the presence of primitive or atypical myeloid or lymphoid cells in the bone marrow and the blood. "A low level of CCNG2 is often associated with poor prognosis and a high recurrence rate such as in the advanced stages of leukemia and in high-grade oral, gastric, and thyroid cancers." (PMID 29720957, 2018).
lung adenocarcinoma (2 papers, 2017 to 2022). A carcinoma that arises from the lung and is characterized by the presence of malignant glandular epithelial cells. "As a result, although PC9 and A549 are both lung adenocarcinoma cell lines, the protein expression of their target genes such as CDKN1A (p21) or CCNG2 may have been different." (PMID 35318440, 2022).
metastatic tumors (2 papers, 2018 to 2024). "In contrast, few metastatic tumors were detected in mice injected with SGC-7901 cells overexpressing cyclin G2." (PMID 30547803, 2018).
myeloid leukaemia (2 papers, 2015 to 2021). "In a study of 228 children with ALL previously treated with anticancer agents including thiopurines, CCNG2 under-expression was a risk factor for treatment-related myeloid leukemia (t-ML)." (PMID 26015807, 2015). "Moreover, the phosphorylation of JNK is controlled by the cyclin CCNG2, which is a direct BMI1 target in myeloid leukaemia." (PMID 34316702, 2021).
osteosarcoma (2 papers, 2014 to 2017). A usually aggressive malignant bone-forming mesenchymal neoplasm, predominantly affecting adolescents and young adults. "In this study, by differential gene expression we found several genes that might be the AR downstream target genes in osteosarcoma, such as cyclin G2, CDC20, Caspase-8, JNK." (PMID 28262798, 2017).
cervical cancer (1 paper, 2017). A primary or metastatic malignant neoplasm involving the cervix. "Since we have also observed that cyclin G2 can exert potent anti-tumorigenic effects, it is possible that inhibition of cyclin G2 by EGFR is a significant event underlying the oncogenic actions of EGF and contributes to ovarian and cervical cancer development." (PMID 28640887, 2017).
depression (1 paper, 2023). "Therefore, it is highly possible that the CCNG2 gene is involved in the onset and development of depression." (PMID 37235790, 2023).
esophageal cancer (1 paper, 2025). A primary or metastatic malignant neoplasm involving the esophagus. "Abnormal expression of CCNG2 had been examined in esophageal cancer, and nasopharyngeal carcinoma." (PMID 40570725, 2025).
gastric tumors (1 paper, 2018). "Moreover, a xenograft model in nude mice was used to determine the effect of cyclin G2 on gastric tumor growth in vivo." (PMID 30547803, 2018). "Moreover, a xenograft model and a metastasis model of nude mice was used to determine the influence of cyclin G2 on gastric tumor growth and migration in vivo." (PMID 30547803, 2018). "Cyclin G2 has been shown to be associated with the development of multiple types of tumors, but its underlying mechanisms in gastric tumors is not well-understood." (PMID 30547803, 2018).
glioblastoma (1 paper, 2018). The most malignant astrocytic tumor (WHO grade IV). "Expression and protein level of CCNG2 were also assessed in glioblastoma cell lines, U138, U251, T98G, and A172." (PMID 29720957, 2018).
head and neck cancer (1 paper, 2016). A primary or metastatic malignant neoplasm affecting the head and neck. "Kaplan–Meier curves based on TCGA data revealed that head and neck cancer patients with reduced CycG2 (CCNG2) expression had poor clinical prognoses." (PMID 27982046, 2016). "Because both CCNG1 and CCNG2 were dysregulated in head and neck cancer, we generated Kaplan–Meier curves and estimated the effect of CCNG1/CCNG2 expression status on survival." (PMID 27982046, 2016).
laryngeal carcinoma (1 paper, 2025). Carcinoma that arises from the laryngeal epithelium. "For instance, miR-210 has been linked to chemotherapy resistance in laryngeal cancer, while miR-93 has been connected to poor prognosis through its targeting of cyclin G2 (CCNG2)." (PMID 39412136, 2025).
melanoma (1 paper, 2024). A malignant, usually aggressive tumor composed of atypical, neoplastic melanocytes. "The delivery of this miR-1246 enhances the invasive capacity of the parental melanoma cell line (BLM) by downregulation of CCNG2." (PMID 39285403, 2024). "We demonstrated that miR-1246 expression affects the protein levels of CCNG2 in our melanoma cell line model." (PMID 39285403, 2024). "In addition, in a public data set (GSE7553) we found that CCNG2 expression is decreased in melanoma metastasis compared to primary melanoma." (PMID 39285403, 2024).
metastatic melanoma (1 paper, 2024). A melanoma that has spread from its primary site to another anatomic site. "Consequently, reduced expression of CCNG2 was associated with poor overall survival in pan cancers as well as in metastatic melanoma." (PMID 39285403, 2024).
oral carcinomas (1 paper, 2021). "miR-1246 has also been found to enhance CCNG2-mediated cancer stemness and drug resistance in oral carcinomas." (PMID 34497267, 2021).
osteoporosis (1 paper, 2014). A condition of reduced bone mass, with decreased cortical thickness and a decrease in the number and size of the trabeculae of cancellous bone (but normal chemical composition), resulting in increased fracture incidence. "Using an animal model of osteoporosis in Ovx mice, which has been widely accepted in the research of PMOP, we showed that cyclin G2 is involved in estrogen-mediated osteogenesis in vivo." (PMID 24595300, 2014).
prostate tumor (1 paper, 2017). "In this set of tumors, the expression of ALDH1A1 and CCNG2 significantly correlates with prostate tumor aggressiveness, in agreement with previous reports." (PMID 28938627, 2017). "Analyses of tumor datasets show that PTOV1 expression significantly correlated with prostate tumor grade, drug resistance (CCNG2) and self-renewal (ALDH1A1, MYC) markers." (PMID 28938627, 2017). "Our study identifies PTOV1, ALDH1A1 and CCNG2 as potential markers of metastasis and bad prognosis when detected in primary prostate tumors." (PMID 28938627, 2017). "These analyses reveal that primary prostate tumors show significantly higher expression of PTOV1, CCNG2 and MYC compared to benign tissue (GSE29079), and PTOV1 levels significantly correlate with CCNG2 and MYC mRNA levels." (PMID 28938627, 2017). "The expression of ALDH1A1, CCNG2 and MYC genes has been reported in aggressive prostate tumors." (PMID 28938627, 2017).
prostatic adenocarcinomas (1 paper, 2017). "ALDH1A1, PTOV1 and CCNG2 transcripts levels are also significantly higher in primary prostatic adenocarcinomas of patients that after radical prostatectomy developed regional or distal metastasis, suggesting their relationship with metastatic progression." (PMID 28938627, 2017).
tuberous sclerosis (1 paper, 2018). Hereditary disease characterized by seizures, intellectual disability, developmental delay, and skin and ocular lesions. "In this study, we demonstrated that cyclin G2 knockout caused increased glomerular hypertrophy, accumulation of mesangial matrix, tuberous sclerosis, and other pathophysiological changes." (PMID 30420966, 2018).
viral infections (1 paper, 2022). "We next sought to determine whether cyclin G2 might also be involved in innate and adaptive immunity in response to bacterial and viral infections." (PMID 36566226, 2022).
cancer (46 papers, 2008 to 2026). A tumor composed of atypical neoplastic, often pleomorphic cells that invade other tissues. "Increased expression of CCNG2 has been associated with cancer metastasis and poor patient outcomes in other malignancies." (PMID 39285403, 2024). "The delivery of miR-1246 results in decreased CCNG2 expression, which is known to be associated with both cancer metastasis and poor patient outcomes." (PMID 39285403, 2024). "Cyclin G2 has been implicated as a tumor suppressor in several cancers because it impedes proliferation, migration, invasion, and cycle cell progression of cancer cells." (PMID 34452627, 2021). "IPA at 4 h revealed that 7 genes [Btg2, Ccng2, Cdkn1a, Gadd45b, Gadd45g, Phlda3, and Mdm2] of 18 genes, which showed statistically significant increases, were associated with cancer, cell cycle, cell death and survival, and cellular growth and proliferation." (PMID 27482301, 2016). "Previous studies have functionally linked the decrease or complete loss of CCNG2 in human cancer to uncontrolled cell proliferation." (PMID 25888956, 2015). "Importantly, miR-1246 expression was associated with cancer cell stemness and chemoresistance through its targeting of the tumor suppressor cyclin G2." (PMID 37189687, 2023). "Several studies indicate that CCNG2 may have an inhibitory role in the progression of cancer as lower expression of CCNG2 is often found in more aggressive cancers and is associated with lower overall survival." (PMID 29720957, 2018). "Cyclin G2 is a potential cancer suppressor gene whose expression may be associated with the pathological process underlying tumor development.The expression levels of cyclin G2 are reduced in thyroid, breast, kidney, stomach, esophageal, pancreatic, and other tumors according to early reports." (PMID 33240810, 2020). "In the TCGA pan cancer dataset, including 33 tumor entities, CCNG2 expression is decreased in metastasis compared to primary tumors and low expression of CCNG2 is also associated with worse patient overall survival and decreased progression free survival." (PMID 39285403, 2024). "In contrast to other cyclins, CCNG2 levels are higher in cycle-arrested cells and mediates growth inhibitory in cancer." (PMID 38902772, 2024). "The cyclin family, which includes genes such as CCNG2, is known to regulate the M phase and is frequently overexpressed in various cancers." (PMID 39689117, 2024). "Taken together, these results provide evidence for a correlation between high miR-1246 levels and the reduction of CCNG2, which explains higher invasiveness of cancer cells leading to metastasis and poorer patient outcomes." (PMID 39285403, 2024). "MiR-1246-mediated targeting of Ccng2 also promotes cancer progression and chemoresistance in other cancers." (PMID 37153758, 2023). "Further analyses exhibited that miR-1246 strengthens the sphere-forming capacity of cells by targeting cyclin G2 (CCNG2), which negatively regulates cancer stemness via inactivating Wingless (Wnt)/β-catenin signaling." (PMID 33799952, 2021). "miR-1246 confers tumorigenicity and affects cancer stemness in OSCC through suppressing cyclin-G2 (CCNG2) CCNG2 has been shown to suppress EMT by disrupting Wnt/β-catenin signaling, which has been proven to be involved in the migration and invasion of OSCCs." (PMID 33917482, 2021). "Although CCNG2 has been found to be connected with cancer stemness and chemoresistance of HNSCC cells, the role of CCNG2 during cell cycle process of HNSCC has not been completely understood." (PMID 34598688, 2021). "Previous research indicated that miR-1246 interacted with CCNG2 expression in different human cancers." (PMID 34497267, 2021). "Although several targets have been found for miR-1249 using bioinformatics tools and luciferase assay, CCNG2 is the most appreciated target of this miRNA in the context of cancer." (PMID 35047553, 2021).